LINC01572 (long independently transcribed non-coding RNA 1572)
Gene: Long non-coding RNA gene on chromosome 16 (72,236,281 to 72,665,083, reverse strand). Ensembl gene ENSG00000261008.
Diseases named in the same sentence as LINC01572 in open-access papers:
LINC01572 is named in the same sentence as 3 diseases in open-access papers, as found by Europe PMC text mining. Sharing a sentence is not in itself a finding about the gene and the disease. The quoted sentences say what the papers report.
gastric cancer (2 papers, 2021 to 2022). A primary or metastatic malignant neoplasm involving the stomach. "LINC01572 is a newly recognized lncRNA molecule, and functionally, only one study reported that it mediated cisplatin resistance in gastric cancer cells." (PMID 34970545, 2021). "The expression of LINC01572 in the blood of cisplatin resistant gastric cancer patients is significantly increased, and it may produce chemotherapy resistance through the mechanism of inducing autophagy." (PMID 36686701, 2022).
hepatocellular carcinoma (2 papers, 2021 to 2023). A malignant tumor that arises from hepatocytes. "The overexpression of LINC01572 significantly increased hepatocellular carcinoma (HCC) cell proliferation, migration, invasion, and epithelial-mesenchymal transition (EMT), whereas the knockdown of LINC01572 had the opposite impact on HCC cells." (PMID 36983670, 2023).
tumor (2 papers, 2021 to 2023). "Additionally, LINC01572 is involved in tumor treatment resistance." (PMID 36983670, 2023).